CTLA4 (cytotoxic T-lymphocyte associated protein 4)
Diseases named in the same sentence as CTLA4 in open-access papers (continued):
Sharing a sentence is not in itself a finding about the gene and the disease.
colon carcinoma (continued). "Some checkpoint-related genes (BTLA, CD80, CD86, CTLA4, IDO1, PDCD1LG2, and TIGIT) had decreased expression in the KRAS-mutated group, providing potential opportunities for immunotherapy in colon cancer." (PMID 33254149, 2020). "Seven checkpoint-related genes (BTLA,CD80, CD86, CTLA4, IDO1, PDCD1LG2, and TIGIT) had decreased expression in the KRAS-mutated group, providing potential opportunities for immunotherapy in colon cancer." (PMID 33254149, 2020). "T-cell co-receptor CD3 was targeted to monitor anti-CTLA-4 treatment in colon cancer xenograft mouse models." (PMID 33584676, 2020). "CT26, a colon tumor model, had the highest immunogenicity and was the model most responsive to CTLA4 inhibitor treatment, by contrast to the relatively low immunogenicity and response rate to checkpoint inhibitor therapies in human colon cancers." (PMID 31898484, 2020). "For PET imaging, CD3 has been used pre-clinically to observe T cell trafficking in bladder and mammary cancer, in addition to monitoring response to CTLA-4 therapy in colon cancer models." (PMID 32582173, 2020). "More recently, in a murine colon cancer model, concurrent treatment with anti-TNFα and combined anti-CTLA-4 and anti-PD-1 improved survival when compared with double checkpoint inhibition treatment alone." (PMID 31439050, 2019). "CT26 colon carcinoma tumor bearing mice were treated with NKTR-214 or CTLA-4 and/or PD-1 checkpoint blockade." (PMID 30400822, 2018). "Previous studies by us and others have revealed that anti-murine CTLA-4 mAb monotherapy is capable of inducing rejection of MC38 colon cancer cells of C57BL/6 origin and CT26 cells of BALB/c origin." (PMID 29463898, 2018). "In the CT26 colon carcinoma model, anti-PD-1 and anti-CTLA-4 combination therapy also elicited tumor rejections that were superior to the individual therapies." (PMID 27610613, 2016). "Similar anti-tumor activity was seen in the experimental pulmonary metastasis model of CT26 colon carcinoma cells, particularly when IL-15SA/IL-15RαSu-Fc was combined with a cocktail of checkpoint inhibitors, anti-CTLA-4 and anti-PD-L1." (PMID 26910920, 2016). "In a CT-26 colon carcinoma model, a combination of an anti-CTLA-4 monoclonal antibody with ixabepilone or paclitaxel resulted in a 50–70% tumor rejection rate." (PMID 26510455, 2015). "An enhanced anti-tumor response at the primary site—as well as an abscopal effect—was observed when fractionated radiotherapy was combined with an anti-CTLA-4 monoclonal antibody in a murine colon cancer model MCA38." (PMID 26510455, 2015). "This is surprising considering a previously published study stating that the tumor-eradicating effect of 4-1BB activation with CTLA-4 blockade in a MC38 colon cancer model is primarily CD8+ T cell dependent." (PMID 25013914, 2014). "CT26 is a N-nitroso-N-methylurethane-induced, undifferentiated colon carcinoma cell line and recent cancer immunotherapy studies have shown that CTLA-4 blockade reduced CT26 colon tumor size and was effective in CT26 tumor models." (PMID 25365349, 2014). "In addition, blockade of PD-1 and CTLA-4 has been found to increase the proliferation of TILs in murine models of colon cancer and ovarian cancer, which express these corresponding immune checkpoints." (PMID 41024300, 2025). "In conclusion, our data indicate that a substantial proportion of patients with localized pMMR colon cancer may benefit from neoadjuvant anti-PD1 plus anti-CTLA4." (PMID 41115454, 2025). "Notably, PRS exhibited a significant positive correlation with mRNA levels of immune checkpoint-associated molecules CD274, CTLA4, LAG3, and TIGIT in colon cancer tissues." (PMID 38577604, 2024). "Our analysis of multiple drug sensitivity databases found that high expression of SERPINC1 may contribute to resistance to anti‐CTLA‐4 therapy in patients with colon cancer." (PMID 38923313, 2024).
colon carcinoma (continued). "Further studies will explore if the L-pampoTM-containing vaccine can also synergize with other ICIs, such as an anti-CTLA-4 antibody, if this combination works in other tumor models such as prostate or colon cancer, and if L-pampoTM, alone or in combination with ICI, affects T-cell memory." (PMID 37568794, 2023). "Furthermore, recent immunotherapies targeting specific immune checkpoints such as PD-1/L1 and CTLA4 have shown promising results in colon cancer treatment, suggesting that the tumor microenvironment plays an important role." (PMID 37563546, 2023). "Furthermore, CTLA-4 expression levels were evaluated using quantitative real-time PCR (Q-RT-PCR) in colon cancer and adjacent colon tissues." (PMID 37107632, 2023). "In a pilot experiment, we sought to evaluate whether BC loaded with anti-CTLA-4 antibodies can efficiently inhibit tumor growth in the MC38 colon cancer model, which is sensitive to CTLA-4 therapy." (PMID 35890247, 2022). "As opposed to the low-risk colon cancer patients, the high-risk cases showed higher expressions of CTLA-4 (p < 0.001), PD-1 (p < 0.01), PD-L1 (p < 0.001), IDO1 (p < 0.05), IDO2 (p < 0.05), HAVCR2 (p < 0.001), and LAG3 (p < 0.05)." (PMID 36280825, 2022). "In addition, 18F-FMISO PET imaging was also applied in preclinical models of breast and colon cancer to probe the tumor and its surrounding microenvironment before and during PD-1 and CTLA-4 checkpoint blockade to quantify tumor hypoxia." (PMID 35538543, 2022). "•Anti-CTLA-4 reduced colon cancer–derived lung metastasis formation in a mouse model." (PMID 35339889, 2022). "Taken together, monotherapy with anti-CTLA-4 might represent an alternative effective strategy against colon cancer to anti-PD-1." (PMID 35339889, 2022). "•Anti-PD-1 and anti-CTLA-4 induced anti-tumor response in colon cancer mouse model." (PMID 35339889, 2022). "Similarly, in the colon cancer model, the combination of vistusertib, an mTOR inhibitor, and anti-CTLA-4, an immune checkpoint blockade, increased the cytotoxic activity of intratumoral CD8+ T cells, by the production of molecules such as IFN-γ and granzyme B." (PMID 36077620, 2022). "We also calculated the ratio of CD8+ cytotoxic T cells / regulatory T cells which is a factor associated with better prognosis in patients with colon cancer and we showed that anti-CTLA-4 increased the ratio, although anti-PD-1 did not." (PMID 35339889, 2022). "Furthermore, anti-CTLA-4 has been shown to increase transcriptional markers of NK cell cytotoxic activity in CT26 colon carcinoma tumors." (PMID 34376232, 2021). "In patients from the GEO dataset, BRAF mutation colon cancer also had higher expressions of CTLA-4 (p = 0.031) and LAG-3 (p = 0.0011), but had no significant expression of PD-1 (p = 0.58)." (PMID 34381786, 2021). "Particularly, the double stimulation of anti-CTLA-4 and anti-PD-1 therapy to improve the immune system can help inhibit the proliferation and liver metastasis of colon cancer cells, and the progression-free survival (PFS) and median survival of patients increase by approximately 37%." (PMID 34367975, 2021). "Therefore, a radiometal-chelated antibody against CD3 ([89Zr]Zr-DFO-CD3) was designed to quantify T-cell infiltration during anti-CTLA-4 treatment in colon cancer xenograft models." (PMID 32327996, 2020). "Relatedly, in breast and colon tumor models, anti-PD-1 or anti-CTLA-4 treatment boosted vessel perfusion through the promotion of CD8+ T-cell accumulation and IFN-γ production, suggesting that improved vessel perfusion was contingent on upregulated T-cell immunity induced by checkpoint blockade." (PMID 33250900, 2020). "Similarly, the T-cell expressed ICI target CTLA-4 has been imaged in preclinical mouse models of colon cancer to better understand target expression and therapy side effects." (PMID 32327996, 2020).
colon carcinoma (continued). "In a murine colon carcinoma model, simultaneous blocking of PD-L1 and CTLA-4 was correlated with an enhanced anti-tumor response, indicating the significance of higher expression levels of immunosuppressive surface molecules by Treg also in colon cancer patients." (PMID 30651930, 2018). "Some of these combinations have potentially less autoimmune side effects than double immune-checkpoint blockade while still having beneficial effects, for example, combination therapy involving anti-CD137 and CTLA-4 blockade in MC38 colon carcinoma tumors and GL261 glioblastoma." (PMID 27847783, 2016). "In murine models of fibrosarcoma (Sa1N) and colon carcinoma (CT26), injection of a single dose of DMAbs (100 μg) encoding murine anti-CTLA-4 resulted in complete responses and suppressed tumor growth similar to 3 doses of recombinant anti-CTLA-4 treatment at 10 ug/injection." (PMID 31373327, 2019). "When BALB/c mice bearing CT-26 colon tumors were treated with anti-PD-1 antibodies as single-agents, there was growth retardation but no eradication of tumors, which notably could be accomplished with dual blockade of PD-1 and CTLA-4." (PMID 26510455, 2015). "Finally, there was a high expression of CTLA-4 on Treg in the human colon tumors." (PMID 22319577, 2012). "Subsequent studies have demonstrated impressive response rates to neoadjuvant PD-1 and CTLA-4 blockade (NICHE-2), and PD-1 and LAG-3 blockade (NICHE-3) in 113 and 59 patients with dMMR locally-advanced colonic cancer respectively." (PMID 41487587, 2025). "The PRS exhibited a significant positive correlation with the infiltration of diverse immune cells, expression levels of related cytokines, and mRNA levels of immune checkpoints CD274, CTLA4, LAG3, and TIGIT in colon cancer tissues." (PMID 38577604, 2024). "IL1B can also enhance the signal transduction of CTLA4, and targeting the IL1B-CTLA4 axis can effectively inhibit the occurrence of metastatic and recurrent colon cancer." (PMID 36969161, 2023). "Immunotherapy is playing an increasingly main role in the current treatment of colon cancer, especially immuno-checkpoint inhibitor (ICI) treatment, including anti-CTLA-4/anti-PD-L1." (PMID 37421455, 2023). "CT26 colon tumour model was used to verify the anti-tumour activity of LC4 in vivo, which has the highest immunogenicity, and is the model most responsive to CTLA-4 inhibitor treatment." (PMID 36195696, 2022). "This work demonstrated anti-cancer effect of CTLA-4 or PD-1 blockade on mouse colon and triple negative breast and on tumor-infiltrating immune cell subpopulations that could improve our knowledge and benefit the breast and colon cancer tumor research community." (PMID 35339889, 2022). "To investigate if the anti-tumor effects of propranolol and its ability to enhance the efficacy of anti-CTLA4 therapy also applied to other cancer types, we performed a similar experiment using the MC38 colon cancer model." (PMID 35017664, 2022). "The results could provide a theoretical basis for clarifying the mechanism of anti-PD-1/PD-L1 or anti-CTLA4 primary drug resistance in colon cancer, and provide a new idea for solving the phenomenon of anti-PD-1/PD-L1 or anti-CTLA4 primary drug resistance in colon cancer." (PMID 36358719, 2022). "We demonstrated again that both monotherapies with anti-CTLA-4 and anti-PD-1 reduced tumor progression in syngeneic CT26 colon cancer." (PMID 35339889, 2022). "Mice bearing syngeneic tumors (MC38 and CT26 murine colon carcinoma and A20 B-cell lymphoma were treated daily with HBI-8000 (orally), alone or in combination with PD-1, PD-1 L, or CTLA-4 antibodies." (PMID 34461854, 2021). "In previous studies, syngeneic colon cancers responding to anti-PD1, CTLA4, or combination therapy displayed increases in CD8+ and GZB+ CD8+ cells and decreases in F4/80 myeloid cells." (PMID 35936114, 2021).
colon carcinoma (continued). "Immune check point antibodies, such as anti-PD1, anti-PD-L1, anti-CTLA4 have led to breakthroughs for the treatment of many tumor types; However, tumor types such as HCC, pancreatic and colon cancers have had relatively low response rates to these antibodies." (PMID 34188068, 2021). "A 64Cu-labelled anti-mouse CTLA-4 antibody was developed and visualized CTLA-4 positive colon tumours in mice." (PMID 31091813, 2019). "Moreover, PAR combines with an anti-CTLA4 antibody enhances cancer cell inhibition, and it also suppresses AOM/DSS induced colon cancer." (PMID 41593769, 2026). "An investigation showed that TIGIT, rather than CTLA-4 or PD-1, was a remarkable factor in NK cell exhaustion in tumor-bearing mice and colon cancer patients." (PMID 40567374, 2025). "In resectable colon cancer, the NICHE study enrolled 62 patients for treatment with neoadjuvant CTLA-4 and PD-1 blockade, and reported a 100% pathologic response rate (defined as > 50% tumour regression) in patients with mismatch-repair deficient (dMMR) disease." (PMID 41487587, 2025). "In colon carcinoma mice treated with anti-CTLA-4 antibodies, increased butyrate and propionate concentrations in the bloodstream led to resistance, increased Treg proportion, and reduced effectiveness of anti-CTLA-4 therapy." (PMID 39767682, 2024). "For instance, anti-CTLA-4 mAbs encapsulated inside the PEGylated liposomes, showed superior capacity for tumor reduction, and favorably changed the CD8+ effector T cell to Treg ratios in mice bearing C26 colon tumors, when compared to free anti-CTLA-4." (PMID 39030582, 2024). "Similarly, CTLA-4 × SIRPα antibody, which targets both CTLA-4 and CD47 on ICOS-high T regulatory cells, enhances antitumor immunity in murine colon cancers." (PMID 36829496, 2023). "Increased CTLA4 levels also correlate with IL-1β expression CC as IL-1β increases the signal transduction of the CTLA4; therefore, targeting the IL-1β–CTLA4 axis may help to overcome the CC immunosuppressive TIME, as seen in colon cancer." (PMID 37508372, 2023). "In addition to SMC1A in the “hot” T‐cell inflammatory microenvironment of colon cancer, SMC1A also positively correlates with the immune checkpoint genes CD274, CTLA4, and PDCD1 in colon adenocarcinoma (COAD) samples." (PMID 37096492, 2023). "In addition, a recent study showed that AMPK induced by a KD enhanced the efficacy of anti-CTLA-4 immunotherapy by decreasing PD-L1 and increasing the expression of type-1 IFN and antigen presenting genes in breast and colon cancer cells." (PMID 36432618, 2022). "In colon cancer, pembrolizumab and nivolumab (anti-PD1 antibodies) have been FDA approved as monotherapy or combined with ipilimumab (anti-CTLA-4 antibody) as treatment for patients with microsatellite instability high (MSI-H)/DNA mismatch repair-deficient (dMMR) mCRC." (PMID 35890355, 2022). "A combination of oral AHCC® and dual immune checkpoint blockade (DICB), including PD-1/CTLA-4 blockade, had reduced tumor growth and increased granzyme B and Ki-67 expression by tumor-infiltrating CD8+ T cells in MC38 colon cancer bearing mice compared to a combination of water and DICB." (PMID 35514996, 2022). "First, the inhibition of the dipeptidylpeptidase DPP4 dampens the CXCL10 degradation, thus improving the CD4 and CD8 T-cell recruitment and limiting the melanoma and colon tumor growth in the presence or not of anti-PD-1 and/or anti-CTLA-4." (PMID 36429101, 2022). "In pre-clinical models the most potent abscopal effects have been observed when CTLA4-anatagonist treatment was applied during RT with 3X8Gy (vs. 5X6 Gy) in breast and colon cancer-bearing mice and not with a single dose of 20 or 30 Gy." (PMID 33816309, 2021). "Antitumor efficacy induced by the three CTLA4 antagonists with or without anti-PD-1 was assessed in the syngeneic CT26 colon carcinoma tumor model as well as in MB49 and MC38 tumor models." (PMID 33127658, 2020).
colon carcinoma (continued). "Similarly, in the colon cancer model (CT26), toxicities observed in the SLC-CTLA4 group were less compared to the group with systemic CTLA-4 blockade (increase in body weight by ~30% compared to ~10%)." (PMID 31373327, 2019). "Furthermore, GVAX plus double checkpoint blockade (anti-CTLA-4 and anti-PD-1) enhanced tumor rejection to 100% in CT26 colon carcinoma and to 75% in ID8 ovarian carcinoma, compared to, respectively, 75 and 50% with double checkpoint blockade only." (PMID 27847783, 2016). "Finally, another study showed that combination of both CTLA-4 and PD1 blocking antibodies with GM-CSF-expressing tumor cell vaccine also efficiently promoted tumor rejection in mouse models of colon carcinoma and ovarian cancer." (PMID 26161423, 2015). "As for possible nanotechnology-driven delivery, in vitro and in vivo studies were performed by Nikpoor and colleagues, who proposed two liposome formulations, one polyethylene glycol (PEG)ylated and the second non-PEGylated, containing anti-CTLA-4 blocking mAb in a C-26 colon cancer model." (PMID 33800368, 2021). "This is of great importance considering the results of a recent study in mice xenografted with human colon cancer cells, suggesting that tumor necrosis factor (TNF) inhibition combined with CTLA-4 and PD-1 immunotherapy may provide a clinically feasible prophylactic strategy regarding some irAEs." (PMID 32325840, 2020). "In our previous studies, we have found that intratumoral NDV could potentiate the efficacy of systemic CTLA-4 blockade in the B16 model, which reasonably supports NDV infection, as well as TRAMP C2 prostate adenocarcinoma and CT26 colon carcinoma, which have poor permissiveness for NDV13." (PMID 28194010, 2017). "To test this hypothesis, we employed CT26, a murine colon cancer model with high CD8+ T cell infiltration, using mock- or ULBP2-transfected tumor cells to examine the impact of ectopic ULBP2 expression under T cell-modulatory conditions with anti-CD4, anti-CD25, and anti-CTLA-4 antibody treatments." (PMID 40558520, 2025). "In summary, combining CRT-NPs with anti-CTLA-4 immunotherapy could be a promising approach to improve the effectiveness of immunotherapy in treating certain types of cancer, specifically, those with T-cell-inflamed tumors such as the CT26 colon carcinoma model used in this study." (PMID 37376141, 2023). "However, whether blocking CXCL8/CXCR1/2 signal or LAG3/LSECtin can increase the efficacy of anti-PD-1/PD-L1 or anti-CTLA4 in patients with colon cancer is still lack of effective experimental verification." (PMID 36358719, 2022). "Collectively, these data demonstrate that the combination therapy of vvDD-IL-9 and the anti-CTLA-4 antibody, but not the anti-GITR antibody, elicited potent systemic tumor-specific antitumor effects in a murine colon cancer model." (PMID 38473379, 2024). "We demonstrated that anti-CTLA-4, but not anti-PD-1, significantly reduced lung weight and metastasis surface in the lung in our CT26 colon cancer model." (PMID 35339889, 2022). "However, neither PD-1/L1 nor CTLA-4 has yet been confirmed to have relevant efficacy in unselected colon cancer, and only the subgroups of deficient mismatch repair (dMMR) or microsatellite instable high (MSI-H) tumors of colon cancer are amenable to checkpoint inhibition." (PMID 34349038, 2021). "For CRC, patients with non-metastatic dMMR colon cancer receiving around 6 weeks of dual blockade of PD1 and CTLA4 and 8 weeks of dual blockade of PD1 and LAG3, respectively in the NICHE2 and NICHE3 studies, and the pCR rates were 67% (72/107) and 79%, respectively." (PMID 38967817, 2024). "In conclusion, the results presented highlight the need to investigate the potential use of alternative immunotherapies for colon cancer that could benefit AA patients regardless of their MSI status and expression of the PDL1 and CTLA4 genes." (PMID 32983990, 2020).
colon carcinoma (continued). "A study using in vivo murine breast and colon cancer models showed that anti–PD-L1 (but not anti–PD-1) monotherapy was able to deplete CD80 ligand expression on tumor-infiltrating antigen-presenting cells, thereby inhibiting CTLA-4 axis through a Treg-dependent mechanism." (PMID 33250900, 2020).